INS (insulin)
Diseases named in the same sentence as INS in open-access papers (continued):
Sharing a sentence is not in itself a finding about the gene and the disease.
metabolic disorders (continued). "The vitamin D receptor (VDR), best known for its role in calcium and phosphate regulation, also impacts immune function and metabolic diseases, influencing insulin sensitivity and inflammatory responses." (PMID 40926269, 2025). "Elevated ROS levels can impair insulin signaling pathways, leading to reduced glucose uptake by cells and contributing to metabolic disorders such as T2D." (PMID 40722566, 2025). "Metabolic disorders such as iron overload, glycolysis, insulin resistance, lipid dysregulation, and glutaminolysis are found to induce liver senescence and ferroptosis, which are hot topics in the research of MASLD." (PMID 39917623, 2025). "This reduction in glucose metabolism lowers insulin demand, helping to maintain lower insulin levels, thereby reducing the incidence of insulin-related metabolic disorders in the liver." (PMID 41502820, 2025). "Interference in insulin signalling has been reported to directly link inflammation in persistent adipose tissue to the manifestation of systemic metabolic disorders in the form of T2DM." (PMID 41226484, 2025). "The product of the two not only quantifies the severity of metabolic disorders but also combines the cumulative effects of visceral fat on insulin signal interference." (PMID 41199862, 2025). "Postprandial exercise attenuates glucose/insulin and is recommended for people with metabolic disease." (PMID 41277758, 2025). "The downregulated genes were involved in fatty acid metabolism and insulin signaling, suggesting a potential role in reducing adiposity and managing metabolic disorders." (PMID 41465164, 2025). "T2DM is a complex, multisystemic metabolic disorder characterized by high blood glucose levels resulting from a progressive defect in insulin secretion or tissue resistance to insulin." (PMID 39940862, 2025). "In metabolic disease models, PCPs have been observed to lower blood glucose levels and improve insulin sensitivity, potentially through the modulation of GM composition and metabolic signaling pathways." (PMID 40649332, 2025). "As women age, insulin sensitivity typically declines, contributing to metabolic disorders and exacerbating ovarian aging." (PMID 40897829, 2025). "Additional experimental approaches, such as fecal microbiota transplantation, have shown promise in improving insulin sensitivity and reducing low-grade inflammation in metabolic disorders." (PMID 41002745, 2025). "The elevated SFA content in adipocyte PLs is of particular concern, as SFAs increase membrane rigidity, potentially impairing insulin sensitivity and promoting the development of metabolic disorders." (PMID 40077693, 2025). "Second, strength training helps improve metabolic disorder states by enhancing skeletal muscle mass and improving insulin sensitivity." (PMID 40746688, 2025). "BPA’s role in metabolic disorders is well established: it disrupts glucose homeostasis by impairing insulin sensitivity and β-cell function." (PMID 41384025, 2025). "Insulin and other growth factors are key regulators of liver gene expression, including in metabolic diseases." (PMID 40228209, 2025). "Thiazolidinediones (TZDs) are a class of PPARγ agonists that have long been used as insulin sensitizers and treatments for metabolic diseases, including MASLD." (PMID 40985048, 2025). "The mTOR dependent mechanisms described give insights into selective insulin resistance in adipocytes and propose novel therapeutic strategies for interventions in the metabolic disease." (PMID 40630101, 2025). "In metabolic diseases, they improve insulin sensitivity and mitigate adipose tissue inflammation, thereby alleviating metabolic dysregulation." (PMID 41246326, 2025). "In metabolic disorders, biomarkers of insulin sensitivity or lipid metabolism can classify patients according to specific disease mechanisms for guiding the choice of interventions, for example, antidiabetic drugs or lifestyle modifications." (PMID 40141854, 2025).
metabolic disorders (continued). "As adipose tissue metabolism has become the main determinant of insulin sensitivity throughout the body, various food-derived bioactive peptides have been proven to alleviate metabolic disorders by regulating the insulin signaling pathway in adipose tissue." (PMID 40941124, 2025). "In conclusion, our study elucidates the mechanism by which DNAJA2 regulates IR endocytosis, insulin signaling and glucose metabolism, shedding light on the pathogenesis of metabolic disorders." (PMID 41233317, 2025). "For metabolic diseases, the findings from this review underscored the potential of mitochondrial-targeted therapies in treating metabolic disorders, such as improved insulin sensitivity and reduced inflammation." (PMID 40134978, 2025). "Clinical studies have demonstrated that FGF21 improves dyslipidemia, reduces body mass, and enhances fasting insulin and adiponectin levels, indicating its potential as a therapeutic agent for metabolic disorders." (PMID 40004991, 2025). "In metabolic disease states characterized by chronic nutrient excess, lipotoxicity, and insulin resistance, this regulatory network becomes disrupted." (PMID 41373947, 2025). "The review examines how adipokines regulate metabolic diseases by affecting critical body functions including inflammation and insulin sensitivity along with energy metabolism." (PMID 40013194, 2025). "Second, advanced glycation end-products contribute to insulin resistance and β-cell dysfunction, leading to glucose metabolism disorders." (PMID 40510488, 2025). "PPARγ agonist, such as TZDs, has also been extensively used to treat metabolic disorders due to their potent insulin-sensitizing properties." (PMID 40985048, 2025). "In particular, mitochondrial dysfunction in adipocytes leads to the progression of metabolic disorders, due to the complex impairment of oxidative capacity, lipid metabolism, insulin sensitivity, adipocyte differentiation, and thermogenesis." (PMID 39704874, 2025). "On the one hand, VD can indirectly attenuate bone damage due to metabolic disorders by increasing insulin sensitivity and improving insulin resistance." (PMID 40547375, 2025). "The bidirectional interaction between the adipose tissue and pancreatic beta cells, known as the adipo-insular axis, where adipokines and insulin are the main components, plays a pivotal role in metabolic regulation and the onset of metabolic disorders." (PMID 40429752, 2025). "T2D is a multifactorial metabolic disorder characterized by insulin resistance and compromised insulin secretion, resulting in chronic hyperglycemia and disrupted glycometabolism." (PMID 40871693, 2025). "The roles of AKT2 and PI3K in metabolic disorders are significant, as both are key components of the insulin signaling pathway." (PMID 41030587, 2025). "DM encompasses a spectrum of metabolic disorders characterized by insufficient insulin secretion, insulin resistance, or a combination of both, leading to impaired regulation of blood glucose levels." (PMID 39811802, 2025). "Dysregulation of these pathways can contribute to cellular dysfunction, metabolic disorders, impaired insulin secretion, and vascular abnormalities." (PMID 40245477, 2025). "Statin use and antidiabetic medication (oral or insulin) were more common in the T2D group, consistent with a higher burden of metabolic disease." (PMID 40863403, 2025). "Blocking the RAAS system shows potential in improving insulin sensitivity and pancreatic β-cell function, thereby ameliorating abnormal glucose tolerance and metabolic disorders." (PMID 40106408, 2025). "NEDD4 suppression ameliorates metabolic disease phenotypes, such as increased lipolytic activity, decreased body weight and improved insulin tolerance, in HFD-fed mice." (PMID 39900792, 2025). "T2 DM is primarily a metabolic disorder characterized by chronic hyperglycemia, which results from defects in insulin secretion, insulin action, or both." (PMID 40565030, 2025).
metabolic disorders (continued). "Research indicates a direct correlation between JUNB expression levels and metabolic disorders, impacting fat metabolism, insulin sensitivity, and inflammatory reactions." (PMID 40918148, 2025). "Bajong with a low GI is highly beneficial in individuals with metabolic disorders, as it promotes better insulin sensitivity, blood sugar regulation, lipid profile improvement, weight management, inflammation reduction and gut health." (PMID 40205494, 2025). "Drugs like TZDs, which act as PPARγ agonists, are used to improve insulin sensitivity and promote glucose uptake in tissues, further emphasizing the importance of PPARγ in metabolic disease management." (PMID 40926269, 2025). "The insulin mimetic property of MI supplementation increases insulin sensitivity and has a positive effect on metabolic disorders, gene expression, inflammatory pathways, OS biomarkers, and hormonal states." (PMID 38370063, 2024). "Polyphenols alleviate metabolic disorders by modulating E3 ubiquitin ligases and the 26S proteasome to mitigate insulin resistance, oxidative stress, abnormal lipid metabolism, and inflammatory responses through regulating the ubiquitin-proteasome system." (PMID 39188976, 2024). "Disruption of mitochondrial homeostasis results in adverse effects on lipid metabolism, adipocyte differentiation, oxidative capacity, inflammation, insulin sensitivity, and thermogenesis, culminating in metabolic diseases." (PMID 38786764, 2024). "For example, genomic markers like MTHFR polymorphisms inform folate supplementation needs, while metabolomic markers such as glucose and insulin levels guide interventions in metabolic disorders." (PMID 39683427, 2024). "The dysregulated interplay between insulin and cellular receptors can instigate a cascade of metabolic dysfunctions, contributing to the pathogenesis of these prevalent metabolic disorders." (PMID 39015535, 2024). "C3 is a fundamental factor in metabolic organs and metabolic diseases, affecting insulin secretion and adipocyte maturation." (PMID 38703299, 2024). "Muscle tissue accounts for 60%–70% of the insulin-stimulated glucose uptake and is described as a primary determinant of metabolic disorders." (PMID 38585221, 2024). "T2DM is a metabolic disease that affects brain structure and function through glucotoxicity, vascular damage, brain insulin resistance, synaptic damage, neuroinflammation, and gliogenesis." (PMID 38952685, 2024). "Sex differences (SDs) are well established in metabolism and metabolic disorders, such as insulin sensitivity, body composition, energy balance, and metabolic disease incidence." (PMID 39048678, 2024). "In obese and high-fat diet states, insulin-mediated FOXA2 repression has been shown to be the molecular mechanism linking lipid-based abnormalities to metabolic disorders." (PMID 38627644, 2024). "In this systematic review, moderate evidence is provided supporting the use of gut-microbiome interventions in improving insulin sensitivity and reducing fasting glucose and lipid levels in patients with metabolic diseases." (PMID 39598283, 2024). "One notable point is that despite the restoration of various physiological factors related to metabolic disease, including insulin sensitivity to NCD levels by PRE consumption, only a partial improvement was observed in the glucose tolerance test." (PMID 38542804, 2024). "MASLD is caused by dysfunction of adipose tissue and an imbalance between metabolic disorders and inflammatory stress induced by insulin resistance and the defense and repair mechanisms of the steatotic liver." (PMID 39604837, 2024). "GIP, an incretin promoter of postprandial insulin secretion alongside GLP-1 has been frequently implicated in glucose homeostasis and is being leveraged for the treatment of metabolic disease." (PMID 38762719, 2024). "Autophagy regulates lipid metabolism, insulin sensitivity, and glucose homeostasis, affecting the development and progression of these metabolic disorders." (PMID 38971910, 2024).
metabolic disorders (continued). "The formation of a complex between ILF2 and S6K protein influences insulin levels and consequently contributes to the progression of metabolic diseases." (PMID 39553470, 2024). "At present, it is reasonable to conclude that very individualized therapies, taking into account interactions of angiotensin peptides, vasopressin, and insulin, should be selected for patients suffering from co-existing cardiovascular and metabolic diseases." (PMID 38279313, 2024). "In metabolic diseases, EVs play a pivotal role by modulating key processes such as insulin sensitivity, lipid metabolism, and inflammation." (PMID 39796048, 2024). "PPAR-α is a transcription factor, considered as a major regulator of lipid metabolism in the liver and has a key role in metabolic diseases because of its triglyceride-lowering and insulin-sensitizing properties." (PMID 37996653, 2024). "By producing metabolites such as HYA, the gut microbiota helps to regulate the host's energy balance and insulin sensitivity, thereby enhancing resistance to metabolic disorders." (PMID 39118186, 2024). "Dietary patterns with a high potential to contribute to insulin hypersecretion and chronic systemic inflammation, based on higher EDIH and EDIP scores, have been associated with multiple metabolic diseases in previous studies." (PMID 39703541, 2024). "Several previous studies indicate that abnormal glucose metabolism is common in NAFLD due to increased gluconeogenesis, disrupted insulin sensitivity, and consequent metabolic disorders." (PMID 38339096, 2024). "Studies have shown that FGF1 reduces blood sugar by increasing insulin sensitivity, providing a new approach for the treatment of metabolic diseases like fatness, NAFLD and T2DM." (PMID 39296548, 2024). "Zinc supplementation decreased fasting blood glucose, hemoglobin A1c, and fasting blood insulin in a meta-analysis of 20 interventional studies performed in healthy persons and individuals with metabolic diseases." (PMID 38337620, 2024). "Modern research has also furnished evidence on the role of inflammation in the onset of pro-inflammatory pathways in insulin production which then lead to the initiation of metabolic disorders including DM38." (PMID 38212326, 2024). "The observed decrease in gluconeogenic enzyme mRNA, like G6Pase and PEPCK, showcases RG saponin’s ability to influence insulin pathways and manage metabolic disorders by fine-tuning critical metabolic processes." (PMID 38998642, 2024). "As well as sharing traits with other diseases and symptoms, PCOS shares many characteristics with metabolic diseases, inflammation, and insulin signaling disorders." (PMID 38468402, 2024). "For instance, children of obese fathers show early signs of metabolic dysfunction, including altered lipid profiles and insulin resistance, conditions that are predictive of future metabolic diseases." (PMID 39770898, 2024). "By identifying the pathways contributing to insulin dysfunction, more effective strategies for preventing and managing metabolic disorders, such as T2D, can be developed." (PMID 39594636, 2024). "Overall, activation of the insulin-independent FAM3A-PANX1-ATP-P2Y receptors signaling pathway is effective in treating metabolic disorders." (PMID 38937853, 2024). "T2DM is a prevalent metabolic disorder characterized by an alteration in carbohydrate metabolism resulting from decreased insulin sensitivity in target tissues along with a relative deficiency of insulin secretion." (PMID 38202001, 2024). "T2DM is characterized by absolute or relative insufficiency of insulin secretion and decreased sensitivity of target organs to insulin, leading to metabolic disorders involving fat, protein, water, electrolytes, and other substrates." (PMID 39062577, 2024). "IR is a metabolic disorder characterized by a decrease in the effectiveness of insulin on tissues in response to normal levels of insulin." (PMID 39310407, 2024).
metabolic disorders (continued). "This concept has been applied to several protein therapeutics, like oral insulin, and they are promising, leading to advancements in this technology to alleviate a range of metabolic disorders." (PMID 39861664, 2024). "IR represents a unique metabolic disorder often characterized by increased insulin levels, which can lead to neurodegeneration and persistent memory impairments due to prolonged exposure of brain neurons to elevated insulin levels." (PMID 39104819, 2024). "DM is a significant chronic condition characterized by inadequate insulin production or the body’s inability to effectively use insulin, leading to a long-term metabolic disorder." (PMID 39408316, 2024). "Recent studies in rodents and humans have shown that pharmacological inhibition of BCKDK significantly improved insulin sensitivity, providing a novel therapeutic target for metabolic diseases." (PMID 39389936, 2024). "This metabolic disorder results from both inadequate insulin secretion by pancreatic β-cells and diminished tissue responsiveness to insulin." (PMID 38611548, 2024). "IR is a pivotal factor in various metabolic disorders, signifying a state where insulin-responsive tissues exhibit reduced responsiveness to physiological insulin levels." (PMID 38904046, 2024). "The etiology of this metabolic disorder is either the insufficient pancreatic production of insulin or resistance to the effects of insulin." (PMID 39452489, 2024). "Intriguingly, the dysregulation of many hormones, such as insulin, glucagon, and sex hormones, is often observed in metabolic diseases, and emerging evidence indicates them as critical regulators of ferroptosis." (PMID 39346540, 2024). "Skeletal muscles account for 60%–70% of the insulin-stimulated glucose uptake and are described as a primary determinant of metabolic disorders." (PMID 38585221, 2024). "A 3-month study involving elderly people with metabolic disorders showed that supplementation with 2000 IU/day of vitamin D significantly decreased the homeostatic model assessment for insulin and decreased oxidative DNA damage." (PMID 39339811, 2024). "Clinical trials have demonstrated that probiotics can improve insulin sensitivity and reduce inflammation in individuals with metabolic disorders." (PMID 39211341, 2024). "Glucagon-like peptide-1 (GLP-1) plays a crucial role in metabolic disorders by enhancing insulin secretion, inhibiting glucagon release, and slowing gastric emptying, thereby improving glycemic control." (PMID 38997662, 2024). "The ensuing fundamental changes lead to reversal of metabolic disease and re-establishment of insulin sensitivity in general, which improves the brain’s insulin sensitivity as well." (PMID 38746934, 2024). "Despite these limitations, our findings affirm the significant potential of RG saponin extract as a natural treatment for enhancing insulin sensitivity and managing metabolic disorders, paving the way for future explorations to harness its full benefits." (PMID 38998642, 2024). "Misaligned insulin signaling, as evidenced in animal and cellular research, disturbed the circadian organization and clock gene expression, ultimately leading to metabolic disorders through elevated production of the PERIOD protein." (PMID 39300516, 2024). "This review summarized the latest research progress of natural polyphenols improving metabolic disorders by regulating lipid accumulation, inflammation, oxidative stress, and insulin resistance through the UPS." (PMID 39188976, 2024). "The metabolic disorders of these intermediates can lead to conditions such as intestinal inflammation, cancer, insulin secretion, histone acetylation, neurological diseases, and NAFLD." (PMID 39850557, 2024). "T2DM is a metabolic disorder in which abnormal insulin activity leads to disturbances in fat metabolism within the body." (PMID 38867152, 2024).